VASH1 (vasohibin 1)
Diseases named in the same sentence as VASH1 in open-access papers (continued):
Sharing a sentence is not in itself a finding about the gene and the disease.
cancer (continued). "Although the precise mechanisms by which VASH1 works remain to be elucidated, these functions of VASH1 can be applied to the inhibition of cancer metastasis." (PMID 24066086, 2013). "The presence of VASH1 in ECs is evident in various cancers, atherosclerotic lesions, age-dependent macular degeneration (AMD), diabetic retinopathy, and rheumatoid arthritis." (PMID 27713261, 2010). "This study revealed the antitumor effect of VASH1 across cancers." (PMID 38010374, 2023). "Compared with IOSE80 cells, the expression of VASH1 was decreased in cancer cells." (PMID 38010374, 2023). "In brief, the present results suggest that VASH1 is differentially expressed in multiple cancers." (PMID 36504559, 2022). "There may be tissue-specific and cancer type-specific mechanisms for VASH1 expression in lymphatic cells." (PMID 30254211, 2019). "Expression of VASH1 has been reported to be increased in a variety of cancers, with poor prognosis." (PMID 29937525, 2018). "Multiple studies, including ours, have examined whether the immunohistochemical staining of VASH1 can be used as a biomarker in various cancer types." (PMID 30623077, 2018). "However, the functional role of VASH1 in directly regulating cancer cell biological characteristics is still under investigation." (PMID 25797264, 2015). "Furthermore, cancer cell-derived VASH1 can directly regulate cell growth, adhesion and migration in vitro, as well as control tumorigenesis and metastasis in vivo." (PMID 25797264, 2015). "Although VASH1 was originally identified as endothelial cell-derived angiogenesis inhibitor, recent studies suggested that its expression is not restricted to the endothelial cells, but also in other types of cells including in cancer cells." (PMID 25797264, 2015). "In addition to the prevalent expression of VASH1 in endothelial cells in cancer stroma, recent studies have shown that VASH1 can express in cancer cells." (PMID 25797264, 2015). "Several recent studies have suggested that VASH1 could be a significant prognostic marker in various types of cancers." (PMID 25797264, 2015). "In addition, knockdown of VASH1 in cancer cells promoted cell growth, adhesion and migration in vitro, and enhanced tumorigenesis and metastasis in vivo." (PMID 25797264, 2015). "In addition, VASH1 expression is critical for regulating cancer cell key biological functions, such as colony formation, adhesion and migration." (PMID 25797264, 2015). "Our results indicate that VASH1 is responsible for the inhibition of cancer metastasis." (PMID 24066086, 2013). "When VASH1 in endothelial cells in culture was knocked-down by siRNA, we observed a decrease in the content of ZO-1, a component of tight junctions, which decrease resulted in increased transmigration of cancer cells across the endothelial cell monolayer." (PMID 24066086, 2013). "Collectively, these results suggest that cancer metastasis was increased VASH1 (−/−) mice, and the intravasation by cancer cells in the primary lesion might be responsible for this increase in metastasis." (PMID 24066086, 2013). "We speculated that endogenous VASH1 took part in the defense against cancer cell intravasation in the primary lesion." (PMID 24066086, 2013). "Moreover, the twin combination of VASH2 inhibition and VASH1 upregulation would be a powerful anti-cancer strategy." (PMID 23426782, 2013). "Indeed, the knockdown of VASH1 enhanced the permeability and transmigration of cancer cells across the homotypic endothelial monolayer." (PMID 24066086, 2013). "Here, we extended our analysis to the role of VASH1 in cancer metastasis." (PMID 24066086, 2013). "As cancers contain complex lesions, where angiogenesis continues asynchronously and sprouting occurs randomly, it is difficult to dissect the expression profile of VASH1." (PMID 27713261, 2010). "However, the contradictory roles of VASH1 and VASH2 in cancers are remaining largely unknown, particularly in association with microtubule detyrosination." (PMID 39443476, 2024).
cancer (continued). "The results that VASH1 expression at normal tissue areas in multiple tumors was higher than in solitary tumors, indicated that hyperactivity of angiogenesis might represent the environment of occurrence of the de novo cancer more often anywhere." (PMID 29535800, 2018). "Indeed, decreased expression of VASH1 correlated with poor prognosis of certain human cancers." (PMID 24066086, 2013). "Here we examined whether VASH1 plays any role in cancer metastasis." (PMID 24066086, 2013). "Compared to non-cancer controls, HNSCC patients showed elevated VASH1 and NO in plasma and VASH1 and iNOS in WBCs." (PMID 40483461, 2025). "miR-1269a can regulate the occurrence and development of cancer by targeting downstream genes (CXCL9, SOX6, FOXO1, ATRX, RASSF9, SMAD7, HOXD10, and VASH1)." (PMID 35252180, 2022). "The recent discovery of Vasohibins (VASH1 and VASH2) as TCPs revitalized the discussion about the role of tubulin detyrosination in cancer." (PMID 33114575, 2020). "In contrast to VASH1, VASH2 is detected at substantially lower levels in differentiated cells, including endothelial cells, but is abundantly expressed in cancer cells and highly undifferentiated cells such as embryonic stem cells." (PMID 29937525, 2018). "The expression level of VASH1 in WBCs was significantly higher in cancer patients compared to non-cancer controls (1.24 ± 0.06 folds, p = 0.0093 by independent t-tests; Kolmogorov–Smirnov test, p > 0.1500)." (PMID 40483461, 2025). "The function of Vasohibin-1 (VASH1) in human cancer has not been thoroughly or comprehensively examined." (PMID 38010374, 2023). "The availability of VASH1/2-SVBP knockout mice will be instrumental in clarifying the apparently opposite roles of VASH1 and VASH2 in cancer and whether this is due to their secreted and/or tubulin detyrosinating activities." (PMID 33114575, 2020). "VASH1 staining of vascular ECs was negative or negligible in GS ≤6 cancer while strong VASH1 staining was observed in GS ≥7 cancer in over half of the cases." (PMID 29535800, 2018). "VASH1-expressing endothelial cells were also co-expressed with CD34 but not with D2-40 in the same vessels in cancer tissues." (PMID 25797264, 2015). "Especially, whether cancer cell-derived VASH1 can influence tumorigenesis and metastasis has not been fully characterized." (PMID 25797264, 2015). "However, we found that no obvious difference of VASH1 or Ephrin-B2 expression was observed between EZH2-overexpressed and EZH2-silenced NPC cells (data not shown), suggesting that the alteration of VASH1 and Ephrin-B2 induced by EZH2 was cell type dependent in cancer cells." (PMID 25237831, 2014).
renal disease (7 papers, 2014 to 2026). "The results of this study suggest that targeting VASH‐1 may represent a specific therapeutic approach for the treatment of renal diseases associated with progressive tissue fibrosis." (PMID 24973329, 2014). "In order to further explore the role of VASH-1 in kidney diseases, we detected VASH-1 levels in high glucose cultured RMCs in vitro and used mannitol for the osmotic pressure control test." (PMID 32754616, 2020). "Previous experimental studies demonstrated the therapeutic effects of VASH1 in murine kidney disease models." (PMID 29937525, 2018). "Second, the renal distribution of VASH1 in renal biopsy specimens taken from patients with kidney diseases was evaluated." (PMID 28835895, 2017). "The present results suggest that the urinary levels of the VASH-1-SVBP complex reflect the disease activity in the relatively acute phase of renal disorders." (PMID 24915146, 2014). "Since the sample size was not large enough to make comparisons among the various renal disorders, the significance of VASH-1 for each particular renal disorder requires further study." (PMID 24915146, 2014). "In conclusion, our present results demonstrated for the first time the potential role of the plasma/urinary level of VASH-1 and the plasma level of the VASH-1-SVBP complex in predicting future renal functional deterioration in patients with renal disorders." (PMID 24915146, 2014). "This is the first study to examine the clinical significance of VASH-1 in patients with renal disorders, indicating the potential of VASH-1 as a predictive biomarker for progressive renal functional deterioration." (PMID 24915146, 2014). "In the present study, we aimed to elucidate the clinical significance of VASH-1 in patients with renal disorders." (PMID 24915146, 2014). "Moreover, it was found that elevated plasma and urinary levels of VASH1 predicted worse renal prognosis in patients with kidney diseases." (PMID 28835895, 2017). "We recently reported the clinical significance of VASH1 in patients with kidney diseases." (PMID 28835895, 2017). "This indicated that both high glucose and Vash1 siRNA can affect VEGF expression, and that VASH-1 can regulate the changes of VEGF levels in high glucose cultured RMCs and play a protective role in kidney diseases." (PMID 32754616, 2020). "However, the circulating and urinary levels of VASH-1 in patients with renal disorders have not been examined to date." (PMID 24915146, 2014). "Notably, studies have suggested that, apart from its association with the progressive decline in renal function, VASH-1 might potentially exert protective effects through negative feedback in renal diseases." (PMID 38791272, 2024). "However, in longitudinal analysis with a three-year follow-up period, higher plasma VASH1 levels predicted composite renal events, defied as a decline in estimated GFR of more than 30% of baseline value, initiation of renal replacement therapy or renal disorder-related death." (PMID 29937525, 2018). "Recent reports show that VASH-1 is present in glomeruli mesangial cells as well, and VASH-1 also plays a potential protective role in kidney diseases via negative feedback." (PMID 32754616, 2020).
infection (3 papers, 2021 to 2026). The state of being infected such as from the introduction of a foreign agent such as serum, vaccine, antigenic substance or organism. "Western blot revealed that the expression level of VASH1 remained steady at both 16-h and 24-h post-infection, whereas VASH2 expression declined upon IAV infection, suggesting that VASH1 is the dominant detyrosination enzyme during IAV-mediated cell death." (PMID 41363857, 2026). "Targeting VASH1-mediated microtubule detyrosination may offer a novel strategy to modulate cell death outcomes during infection and inflammation." (PMID 41363857, 2026). "In the absence of VASH1 overexpression, pyroptosis was the predominant form of cell death, but apoptotic cell death increased with the progression of infection (orange, necroptotic; blue, apoptotic)." (PMID 41363857, 2026).
VASH1 also shares sentences with these, for which no sentence is quoted: Bladder Cancer (2 papers); non-small cell lung carcinoma (2); urothelial carcinoma (2); adenocarcinoma (1); age-related macular degeneration (1); arteriosclerosis (1); cardiovascular diseases (1); cervical tumors (1); cholera (1); diabetic retinopathy (1); epilepsy (1); heart failure (1); Hyperglycemia (1); invasive ductal carcinomas (1); Pan (1); peripheral vascular disease (1); squamous cell carcinoma of the esophagus (1); type 1 diabetic nephropathy (1); upper tract urothelial carcinoma (1); viral infection (1).